CD70 (CD70 molecule)
Diseases named in the same sentence as CD70 in open-access papers (continued):
Sharing a sentence is not in itself a finding about the gene and the disease.
melanoma (continued). "Here, we show that RhoA, BRAF and Mitogen Activating Protein Kinase pathways are involved in the positive transcriptional regulation of CD70 expression in melanomas." (PMID 26828592, 2016). "We used a siRNA strategy to reduce RhoA, RhoB, or RhoC expression in CD70+ LB1319-MEL human melanoma cells." (PMID 26828592, 2016). "In melanomas, like for CD70, the expression of 1α-Hydroxylase (CYP27B1), the enzyme responsible for the synthesis of vitamin D, decreases during the progression of the disease." (PMID 26828592, 2016). "We recently showed that CD70 was expressed in most primary melanomas and that its expression was lost over the course of melanoma progression." (PMID 26828592, 2016). "To test MAPK pathway implication in the regulation of melanoma-expressed CD70, we used two specific pharmacological inhibitors of MEK phosphorylation (p-MEK): PD98059 (data not shown) and U0126." (PMID 26828592, 2016). "Most primitive melanomas contain CD70-positive tumor cells, and this expression decreases during the progression of the disease and in metastasis." (PMID 26828592, 2016). "Here, using three other human melanoma cell lines we have shown that RhoA, rather than RhoC, controls the migration and invasive capacities of melanoma cells through its positive regulation of melanoma-expressed CD70." (PMID 26828592, 2016). "T. Boon for the human melanoma cell lines, Dr. B. Richardson for the CD70 Luc reporter promoter, and Dr. A. Olichon and Cathy Bouchenot for the RhoA-coding adenovirus." (PMID 26828592, 2016). "In a promising clinical trial for advanced melanoma, autologous DCs were electroporated with mRNA encoding CD40L, a constitutively active TLR4 and CD70 (TriMix), thereby improving DCs immunostimulatory capacity." (PMID 26042126, 2015). "We report novel detection of CD70 expression in multiple cancers including pancreatic (25%), larynx/pharynx (22%), melanoma (16%), ovarian (15%), lung (10%), and colon (9%)." (PMID 20664585, 2010). "We have previously shown that melanoma cells expressing high levels of CD70 alone or in combination with CD80 induced in vitro splenocyte proliferation." (PMID 15279677, 2004). "In murine cells (either fibroblasts or melanoma cells), a high percentage of cells only expressed CD70." (PMID 15279677, 2004). "In the present study, using data from two observational prospective cohorts, we aimed to determine whether the predictive value of sCD27 in anti-PD-1 therapy resistance, as observed previously, extends to melanoma, known to express CD70." (PMID 40148586, 2025). "TriMix has been mostly used as a DC-based mRNA vaccine against melanoma because it encodes the activation stimulator CD40L (CD4+ T-cell activator), the costimulatory molecule CD70 (CD8+ T-cell activator), and the constitutively active TLR 4 (DC antigen presentation promotor)." (PMID 37726283, 2023). "As such, CD70 expression has been reported on both primary and metastatic tumor resections in renal cell carcinoma, nasopharyngeal carcinoma, glioblastoma, melanoma, lung carcinoma, cervix carcinoma, breast carcinoma, ovarian carcinoma and mesothelioma and was associated with decreased survival." (PMID 34991665, 2022). "CD70 has also been associated with tumor epithelial to mesenchymal transition (EMT), a process by which epithelial cells gain migratory and invasive characteristics in glioblastoma, melanoma, pancreatic carcinoma and NSCLC." (PMID 34991665, 2022). "Except CD70, all these genes have been reported in human melanoma as well." (PMID 34885093, 2021). "To address this problem, we designed a bivalent tandem CAR (TanCAR) targeted two pan-tumor-associated antigens, CD70 and B7-H3 (CD276), which could also apply for the immunotherapy of multiple types of solid tumor and melanoma." (PMID 32685008, 2020). "In summary, we have shown in a cohort of tumor types that overexpressed both CD70 and B7-H3, and we developed a TanCAR construct which might be applied in treating multiple solid tumors and melanoma." (PMID 32685008, 2020).
melanoma (continued). "For example, one study in C57BL/6 mice bearing B16gp melanoma tumors demonstrated that local irradiation with a single high dose of 10 Gy resulted in upregulation of CD70 and CD86 on local DCs, both of which are co-stimulatory molecules involved in T-cell priming." (PMID 28123900, 2016). "However, the correlation between Rho GTPases, BRAF and MAPK pathway activation status and CD70 expression in CD70+ melanoma cells is yet to be described." (PMID 26828592, 2016). "In this study, we investigated the roles of Rho GTPases on CD70 expression in human melanomas." (PMID 26828592, 2016). "Here we have shown that RhoA and MAPK pathway cross-talk to regulate melanoma-expressed CD70." (PMID 26828592, 2016). "Interestingly, the clinical inhibitor of the common BRAF V600E/D variants, Vemurafenib (PLX-4032), which is currently used to treat melanoma patients with BRAF V600E/D-mutated metastatic melanomas, decreased CD70 expression in human CD70+ melanoma cell lines." (PMID 26828592, 2016). "To test this hypothesis, we evaluated MAPK pathway activation in CD70+ melanoma cells (LB1319-MEL and WM-266-4) after simultaneous silencing of CD70 and treatment with PLX-4032." (PMID 26828592, 2016). "The role of the BRAF/ERK pathway on CD70 expression in melanoma cells was also investigated here because this pathway is essential in melanoma progression and metastasis, and because pharmacological inhibitors have a strong but often transitory efficacy against these tumors." (PMID 26828592, 2016). "We next tested the implication of the MAPK pathway in the regulation of melanoma- expressed CD70, because this pathway is involved in TNF family protein regulation and is activated in many melanomas, where it plays an essential role in melanoma progression and metastasis." (PMID 26828592, 2016). "Indeed, we have demonstrated here that the MAPK pathway positively regulates CD70 expression in melanoma cells." (PMID 26828592, 2016). "Melanoma cells expressing monomeric CD70 possessed reduced ability to migrate and invade surrounding areas, whereas the trimerization of CD70 increased the invasive potential of melanoma through MAPK pathway activation, RhoE overexpression and inhibition of actin fibers and focal adhesions." (PMID 26828592, 2016). "Since Rho GTPases are involved in tumor mobility and that we had previously shown that RhoA regulates the expression of another member of the TNF family (FasL) in melanoma cells, we tested for potential roles of Rho GTPases in the regulation of CD70 expression." (PMID 26828592, 2016). "In addition, we used BRAF specific siRNAs, PLX-4032 and several inhibitors of the MAPK pathway to investigate the role of this pathway in the regulation of CD70 expressed by melanoma cells." (PMID 26828592, 2016). "Considering the frequent expression of CD70 in various tumors beyond melanoma and renal cell carcinoma, such as nasopharyngeal carcinoma, mesothelioma, and glioblastoma, the predictive value of sCD27 may hold promise for broader application across various cancer types." (PMID 40148586, 2025). "Some studies in melanoma have generated TME transcriptome profiles from responders and non-responders receiving ICB45,46, and computational analysis of these profiles illustrated that CD70 expression was associated with T-cell dysfunction and inferior ICB outcomes." (PMID 37024479, 2023). "TriMix, a mixture of monocyte-derived dendritic cells electroporated with mRNA encoding CD70, CD40 ligand, and constitutively active TLR4, as well as the tumor-associated antigens tyrosinase, gp100, MAGE-A3, or MAGE-C2 were administered together with ipilimumab in patients with advanced melanoma." (PMID 36830845, 2023). "RhoA silencing can lead to the expression decline of CD70, while the overexpression of RhoA can induce the significant increase of CD70 expression, suggesting that RhoA may be related to the inhibition of melanoma." (PMID 28404912, 2017).
melanoma (continued). "For instance, autologous DCs electroporated with mRNA encoding CD40L (plus CD70 and TLR4) and fusion protein of an HLA class II-targeting signal (DC-LAMP) and melanoma-associated antigens (TriMixDC-MEL) were immunogenic and generated tumor responses in chemorefractory melanoma." (PMID 26082780, 2015). "In this study, we first characterized the intratumoral expression of CD70 and CD27 in melanoma tumors and their interaction in vivo." (PMID 40148586, 2025). "In a melanoma mouse model generated by injecting the A375 melanoma cell line, treatment with TanCAR-T cells led to a more pronounced reduction in tumor burden compared to controls and the single-target CAR (CD70 or B7-H3) groups." (PMID 40092990, 2025). "In melanoma, several antigenic targets, including c-MET, CD70, VEGFR2, and GD2, have been investigated due to their roles in tumor growth, angiogenesis, and immune evasion." (PMID 40094890, 2025). "We have shown that the tumor of melanoma patients is well infiltrated by CD8+ T lymphocytes expressing CD27, which interacts with the CD70 molecule." (PMID 40148586, 2025). "Preclinical studies have identified various potential future targets for targeted melanoma therapy, including CD126, chondroitin sulfate proteoglycan 4 (CSPG4), tandem CD70 and B7-H3, and αvβ3 integrin." (PMID 38399429, 2024). "Current preclinical studies have identified new potential targets for precision melanoma therapy, including CD126, chondroitin sulfate proteoglycan 4 (CSPG4), tandem CD70 and B7-H3, and αvβ3 integrin." (PMID 38399429, 2024). "CAR-T/NK cell therapy for melanoma is developing rapidly, and clinical experiments using CAR-T cells are currently investigating c-MET, CD70, GD2, and VEGFR2 as melanoma-specific antigens." (PMID 38057843, 2023). "Melanoma-specific antigens that are currently under investigation in clinical trials using CAR-T cells include c-MET, CD70, GD2 and VEGFR2." (PMID 34572949, 2021). "A melanoma mouse model treated by TanCAR T cells exhibited a more pronounced reduction in tumor burden, when compared to controls, and to single CAR (CD70 or B7-H3) groups." (PMID 34207884, 2021). "Another review on this topic also discussed the future promise of several molecular targets for CAR T cell therapy in melanoma, including CSPG4, GD2, CD70, CD20, gp100, and NY-ESO-1." (PMID 34207884, 2021). "In fact, molecular targeted therapy against both CD70 and HIF-2α is currently undergoing clinical trials with antibodies against CD70 for renal cell carcinoma, melanoma, lymphomas and other cancers as well as a HIF-2α inhibitor for renal cell carcinoma." (PMID 29721188, 2018). "Administration of ex vivo-activated B-cells co-expressing CD40L along with other costimulatory ligands CD70 and OX40L gave substantial antitumor effects in a B16 melanoma model." (PMID 27323820, 2016). "B-cells co-expressing CD40L with CD70, OX40L, or 4-1BBL induced potent therapeutic antitumor effects in a B16 melanoma model." (PMID 27323820, 2016). "We have previously shown that the enhancement of the active trimeric form of CD70, facilitated by the binding of the CD70-specific mAb QA32, induced MAPK pathway hyper-activation, which favored melanoma cell invasion." (PMID 26828592, 2016). "But interestingly, by silencing CD70 in CD70+ melanoma cell lines we show that PLX-4032-induced melanoma cell killing and its inhibitory effect on MAPK pathway activation are unaffected by CD70 expression." (PMID 26828592, 2016). "Adoptively transferred CD70-expressing immature DCs were capable of priming CD8+ T cells into effectors, to control B16 melanoma tumor growth, to generate complete tumor rejection, and to induce memory CD8+ T cells." (PMID 26042126, 2015). "Recent studies have shown an involvement of immune system dysregulation in pathophysiology of mucosal melanomas with identification of certain genes like IL17A and CD70." (PMID 24995141, 2014).
melanoma (continued). "To facilitate the translation of CD70 blockade in other CD70-high solid tumors, we found CD70 also significantly influenced ICB outcomes and T cell dysfunction in melanoma patients, and CD70-KO inhibited orthotopic melanoma growth without interfering with tumor cell proliferation." (PMID 37024479, 2023). "The evaluation of CD70 in combination with CD5 and CD117 or preferentially expressed antigen in melanoma in combination with CD5 and CD117 may help to diagnose thymic squamous cell carcinoma (TSCC) more accurately." (PMID 36088333, 2022). "The involvement of CD70 in the generation and/or maintenance of a CSC phenotype has been described in breast cancer, glioblastoma, melanoma, pancreatic carcinoma and non-small cell lung cancer (NSCLC) and thus could serve as a potential marker of stem cells." (PMID 34991665, 2022). "Silencing BRAF in these melanomas inhibited MAPK pathway activation, which is illustrated by the reduction of ERK phosphorylation, so we tested the involvement of BRAF protein in melanoma-expressed CD70 using a BRAF specific siRNA." (PMID 26828592, 2016). "But we have also shown that the interaction of melanoma-expressed CD70 with the MAPK pathway does not interfere with the inhibitory activities of PLX-4032 (Vemurafenib) in melanoma cells on MAPK pathway activation and melanoma cell survival." (PMID 26828592, 2016). "We wondered if CD70 expression in melanomas might interfere with PLX-4032-induced inhibition of MAPK pathway activation and PLX-4032-induced melanoma killing." (PMID 26828592, 2016). "As CD70 is not expressed in all melanoma cells we choose three cell lines highly expressing CD70: LB1319-MEL (100% CD70+), LB39-MEL (CD70+ clones we isolated) and WM-266-4 (100% CD70+)." (PMID 26828592, 2016). "Despite this similitude in the evolution of CD70 and CYP27B1 expression during melanoma progression, we have observed that the expression of CD70 and melanin are not correlated in the melanoma cell lines used in this study." (PMID 26828592, 2016). "This information is essential for the clinical use of Vemurafenib, to know that presence or absence of CD70 in melanoma patient tumor cells will not affect the efficacy of Vemurafenib treatment." (PMID 26828592, 2016). "Next, NK cells were sorted according to their expression of CD8α and CD70 and tested for their cytotoxicity against classical NK target cell lines 721.221 (B cell lymphoma) and K562 (myeloid leukaemia), as well as non-hematological tumor cell lines PC3 (prostate), A549 (lung) and Colo829 (melanoma)." (PMID 40046047, 2025). "Finally, this lipid-driven immunosuppressive mechanism induced by CD70-CD27 signaling opens CD70-targeted precision therapy as additional avenue for NPC patients, and is potentially feasible and effective in patients with melanoma, depending on their specific TME landscapes." (PMID 37024479, 2023). "In addition, an increase in the levels of trimeric CD70 at the outer membrane can activate MAPK/PhoE signalling and may instead enhance melanoma cell invasiveness." (PMID 33050615, 2020). "Consequently patients' biopsies do not need to be tested for CD70-melanoma expression before treatment of patients with Vemurafenib treatment and it does not interfere with the treatment efficacy." (PMID 26828592, 2016). "Rho GTPases activity is central to melanoma cells, and indeed we have previously shown that RhoA inhibition induced the up-regulation of several immune-interacting molecules including MHC Class-I, CD80/CD86 costimulatory molecules and FasL, which like CD70 belongs to the TNF superfamily." (PMID 26828592, 2016). "The observed membrane-expressed CD70 down-regulations induced by siRhoA2 transfection or U0126 treatment were not increased by the combination of both treatments, indicating that RhoA and MAPK pathway have no additive effects on the regulation of melanoma-expressed CD70." (PMID 26828592, 2016).
melanoma (continued). "Indeed LB1319-MEL cells are CD70 and melanin positive and WM-266-4 are CD70 positive and they express low a level of melanin, and among our CD70 negative melanoma cell lines certain are melanin positive and other are negative." (PMID 26828592, 2016). "Consequently, our work demonstrates that CD70 ectopic expression in melanomas is not a valuable biomarker to predict tumor cells sensitivity to BRAF V600 inhibitors." (PMID 26828592, 2016). "Altogether these results showed that melanoma-expressed CD70 does not interfere with PLX-4032 effects, suggesting that CD70 is not a biomarker of melanoma sensitivity to Vemurafenib (PLX-4032) treatment." (PMID 26828592, 2016).